GCG (glucagon)
Diseases named in the same sentence as GCG in open-access papers (continued):
Sharing a sentence is not in itself a finding about the gene and the disease.
type 2 diabetes (continued). "Dysregulated glucagon secretion from pancreatic alpha-cells is a key feature of type-1 and type-2 diabetes (T1D and T2D), yet our mechanistic understanding of alpha-cell function is underdeveloped relative to insulin-secreting beta-cells." (PMID 35304577, 2022). "In recent years, investigators have recognized that glucagon and the hormonal effects of glucagon play a central role in the pathogenesis of type 2 diabetes." (PMID 36334626, 2022). "When it comes to postprandial changes in glucagon concentrations, results are even more puzzling and the detailed contribution in the pathogenesis of type 2 diabetes is still unclear." (PMID 35872982, 2022). "Despite their differences in etiology and pathogenesis, both type 1 (T1D) and type 2 diabetes (T2D) present dysfunctional glucagon-producing α-cells and impaired glucagon secretion." (PMID 36613676, 2022). "Since patients with type 2 diabetes show elevated fasting glucagon levels, the hormone has been believed to be a relevant contributor to hyperglycemia." (PMID 35872982, 2022). "Patients with type 2 diabetes have disproportionately elevated fasting glucagon levels and also exhibit reduced early glucose-induced suppression of glucagon secretion in response to an oral glucose tolerance test (OGTT)." (PMID 33407418, 2021). "We will initially focus on insulin and glucagon signaling pathways which are deregulated in type 2 diabetes." (PMID 34319011, 2021). "In type 2 diabetes, the ability of insulin to suppress endogenous glucose production is impaired, and increased fasting and postprandial glucagon levels stimulate endogenous glucose production even further." (PMID 34382579, 2021). "Glucagon activates AMPK activity to regulate glucose metabolism during fasting, and abnormal glucagon secretion is associated with type 1 and type 2 diabetes." (PMID 34738906, 2021). "Our results indicate that genetic influence of fasting glucagon levels and suppression of glucagon secretion during an OGTT have a limited impact on type 2 diabetes development." (PMID 33407418, 2021). "Many individuals who develop type 2 diabetes also display increased glucagon levels (hyperglucagonaemia), which we have previously found to be associated with the metabolic syndrome." (PMID 33275161, 2021). "During hyperglycemia, plasma glucagon was equally suppressed, although significantly higher in the group of patients with type 2 diabetes compared to controls." (PMID 34085953, 2021). "Increased plasma glucagon concentration (hyperglucagonaemia) has been suggested to play a crucial role in the development of type 2 diabetes." (PMID 33275161, 2021). "Both type 1 and type 2 diabetes patients frequently manifest inappropriate glucagon secretion that contributes to the deterioration of glycemic control." (PMID 33839150, 2021). "DPP-4 inhibitors are known to be effective in the treatment of type 2 diabetes by regulating insulin and glucagon secretion with few major side effects." (PMID 34205264, 2021). "This is particularly important in subjects with type 2 diabetes, as they often have inappropriately elevated levels of glucagon in spite of hyperglycemia; the hyperglucagonemia, in turn has been demonstrated to contribute importantly to the hyperglycemia." (PMID 34168620, 2021). "A recent study showed that up to 40% of alpha cells in human islets obtained from healthy donors contain both GLP-1 and glucagon and this proportion increases to 60% in islets from donors with Type 2 diabetes." (PMID 34659118, 2021). "Recent work have highlighted the existence of a liver alfa‐cell axis and reported that this axis is compromised in individuals with type 2 diabetes and prediabetic states in terms of failure of the liver to increase ureagenesis in response to glucagon." (PMID 34405569, 2021). "For example, intestinal microorganisms can alter the synthesis and secretion of insulin and glucagon, which is closely related to type II diabetes mellitus in animals." (PMID 32832271, 2020).
type 2 diabetes (continued). "Several previous studies reported that treatment with an SGLT2 inhibitor for 1–12 weeks significantly increased fasting or postprandial plasma glucagon levels in type 2 diabetes patients." (PMID 32337293, 2020). "The rationale for the use of GRAs and glucagon agonists in the treatment of patients with type 2 diabetes (55–68% of whom have liver steatosis) and obesity is based on glucagon’s effects on hepatic glucose and lipid metabolism, respectively." (PMID 33333850, 2020). "Sitagliptin is dipeptidyl peptidase-4 (DPP-4) inhibitor, is used to treat diabetes mellitus type II as it increases the production of insulin and decreasing the production of glucagon by the pancreas." (PMID 32298346, 2020). "Biguanides (brands include: Metformin, Diabex and Diaformin) are the most common class of medication used to control hyperglycemia of type 2 diabetes, and work by inhibiting glucose release from the liver by suppressing hepatic glucagon signaling." (PMID 32512650, 2020). "This prediction is relevant for the impaired glucagon response to hypoglycemia and hyperglucagonemia observed in type 2 diabetes." (PMID 33281631, 2020). "The insulin resistance state of pancreatic α-cells seems to be related to glucagon hypersecretion in type 2 diabetes." (PMID 33020399, 2020). "In type 2 diabetes (T2D), in contrast to the physiologic state, glucagon hypersecretion arises in hyperglycemic conditions, while glucagon hyposecretion occurs in the hypoglycemic state, leading to increased plasma glucose and/or prolonged hypoglycemia." (PMID 33020399, 2020). "The suppression of glucagon secretion following a glucose bolus was also blunted in individuals with type 2 diabetes." (PMID 32987824, 2020). "The glucagon pathway is suspected of being the target of BBR beyond the insulin pathway because abnormally elevated glucagon levels and increased hepatic glucagon sensitivity drive hepatic gluconeogenesis in type 2 diabetic patients." (PMID 31976031, 2020). "This relationship is important for the postprandial suppression of glucagon secretion and is lost in type-2 diabetes and pre-diabetes." (PMID 32312960, 2020). "Impaired glucagon suppression in response to glucose or meal challenges was described in previous studies in subjects with prediabetes and type 2 diabetes and was reported as a key pathophysiologic feature of type 2 diabetes and altered glucose tolerance." (PMID 31546230, 2019). "One study found that in patients with type 2 diabetes, tirzepatide decreased glucagon concentrations despite concomitant lowering of plasma glucose, much like a GLP-1RA, but with greater magnitude." (PMID 31443356, 2019). "GLP-1 has another beneficial effect in type 2 diabetes that contributes to maintaining euglycaemia: in type 2 diabetes glucagon secretion is excessively stimulated and glucagon stimulates hepatic glucose production." (PMID 31275246, 2019). "Administration of GLP-1 suppresses glucagon secretion in patients with type 2 diabetes, as measured using a glucose clamp test." (PMID 31357734, 2019). "In our study, decreased glucagon levels, and increased insulin levels were observed in type 2 diabetes group." (PMID 30674322, 2019). "A known characteristic of patients with type 2 diabetes is dysregulated glucagon secretion and many have consequently focused on glucagon antagonism." (PMID 31284506, 2019). "While IL-1β, glucagon and Apo-B are individual markers for type 2 diabetes, PDGF-BB, IL-13, eotaxin, Apo-E, and Apo-CII are the individual markers for the CAD group." (PMID 30674322, 2019). "(Orally administered glucose has, however, been reported to increase plasma concentrations of glucagon in healthy subjects and in patients with type 2 diabetes)." (PMID 31284506, 2019).
type 2 diabetes (continued). "One is that the development of DPP-4 inhibition is a rational drug design based in scientific studies on pathophysiology of type 2 diabetes and that the development shows that it is important to target both the impaired insulin secretion and the high glucagon." (PMID 31275243, 2019). "It will be relevant to study the fixed ratio of glucagon and insulin in a type 2 diabetic animal model where a higher insulin dose is needed because of more insulin resistance." (PMID 29595915, 2018). "Disturbances in suppression of mealtime glucagon concentration are also present in type 2 diabetes patients, whose hepatic glucose production contributes to hyperglycemia." (PMID 29976929, 2018). "Supportive of a potential fear modulating role for glucagon, type II diabetes patients, which have both elevated insulin and glucagon levels, have an increased risk to develop anxiety disorders (OR = 1.25 (CI 1.10–1.39))." (PMID 30210279, 2018). "Paradoxically, by year 5 of disease duration in type 1 diabetes and in long-duration, reduced C-peptide type 2 diabetes, glucagon secretion during hypoglycaemia is markedly impaired." (PMID 29417183, 2018). "GCK-MODY patients displayed increased and earlier glucagon responses during hypoglycemia compared with a group of glycemia-matched patients with type 2 diabetes." (PMID 30146176, 2018). "Late diabetes type 2 is characterized by long persistence of high postprandial plasma glucose levels, reduced insulin levels (hypo-insulinemia) and elevated glucagon levels (hyper-glucagonemia)." (PMID 30631280, 2018). "Impaired suppression of glucagon by insulin and glucose have been proposed as potential mechanisms for the hyperglucagonemia observed in individuals with type 2 diabetes (T2DM)." (PMID 28881681, 2017). "Glucagon plays a central role in systemic glucose homeostasis by stimulating hepatic glucose production, and oversecretion of glucagon contributes to the hyperglycemia in type 2 diabetes." (PMID 28575322, 2017). "Together, they point to the importance of functional defects in the insufficient secretion of insulin and excessive secretion of glucagon in type-2 diabetes." (PMID 28887444, 2017). "In isolation, the catabolic and thermogenic actions of glucagon would be beneficial to individuals who are obese or have type 2 diabetes but these actions are inherently paired with the undesirable stimulation of gluconeogenesis and glycogenolysis." (PMID 28733905, 2017). "This improves glycemic control in patients with type 2 diabetes, primarily by suppressing glucagon levels and increasing endogenous insulin secretion." (PMID 29340105, 2017). "Our findings in the present study are in concert with our previous observation in patients with type 2 diabetes that glucagon secretion concomitantly decreases with insulin secretion." (PMID 29162828, 2017). "In type-2 diabetes, both insufficient insulin and excessive glucagon secretion contribute to hyperglycemia." (PMID 28887444, 2017). "Elevation of AUC−15–240 min-glucagon by FR in type 2 diabetes and by MR in type 2 diabetes and controls reached statistical significance." (PMID 26704625, 2016). "Inappropriate glucagon levels in blood are observed in fasting and after a meal in both type 1 and type 2 diabetes patients." (PMID 27382574, 2016). "These pathways are insulin signaling pathway, insulin resistance, glucagon signaling pathway, type II diabetes mellitus, AMPK signaling pathway, PPAR signaling pathway, and malaria." (PMID 28224024, 2016). "We recently have reported the 24-hour glucose, insulin and glucagon responses to a 72-hour fast compared to a 72-hour macronutrient-sufficient, carbohydrate-free diet in men with type 2 diabetes." (PMID 27453716, 2016). "Levels of glucagon and AUC−15–240 min-glucagon were elevated by FR and MR in type 2 diabetes and controls, when compared with RF." (PMID 26704625, 2016).
type 2 diabetes (continued). "In contrast to GIP, which increases glucagon secretion both in controls and in type 2 diabetes subjects, GLP-1 reduces glucagon secretion in addition to increasing insulin secretion." (PMID 27382574, 2016). "Type II diabetes is characterized through decreased insulin secretion, long-term high blood glucose and increased glucagon release." (PMID 27013590, 2016). "Increased levels of glucagon in type 2 diabetes are well known and, until now, have been considered deleterious." (PMID 27568179, 2016). "Unrestrained hepatic glucose output and elevated glucagon secretion make an important contribution to the development of hyperglycaemia in type 2 diabetes." (PMID 26512980, 2015). "The data regarding the pattern of α-cells and glucagon in pathologic states such as obesity, insulin resistance and type 2 diabetes in both humans and rodents are highly controversial." (PMID 25923733, 2015). "GCGR based inhibitors for the treatment of type 2 diabetes are either glucagon neutralizing antibodies or small molecular antagonists." (PMID 26236379, 2015). "GCGR based inhibitors for the treatment of type 2 diabetes are either glucagon neutralizers or small molecular antagonists." (PMID 26236379, 2015). "Our data suggest that CD38/cADPR-mediated Ca2+ signals play a key role in glucagon-induced gluconeogenesis in hepatocytes, and that the signal pathway has significant clinical implications in metabolic diseases, including type 2 diabetes." (PMID 26038839, 2015). "Under normal physiological conditions, serum glucagon concentration immediately decreases after a meal, whereas in subjects with type 2 diabetes, it can even be found to be elevated after a meal." (PMID 26378455, 2015). "Inappropriately elevated plasma glucagon concentrations play a role in dysregulated hepatic glucose production and abnormal glucose homeostasis in type 2 diabetes." (PMID 24838678, 2014). "It potentiates insulin secretion, blocks glucagon release and increases satiety, but cannot be used directly as a therapy for Type 2 diabetes due to its short (2 minute) half life." (PMID 24835252, 2014). "As excessive α-cell glucagon secretion is an important contributor to hyperglycemia during type 2 diabetes, the ability to lower glucagon secretion is one of the main therapeutic advantages of incretin-based therapy." (PMID 23781322, 2013). "Type 2 diabetes (T2D) is associated with loss of glucose-induced suppression of glucagon secretion—indeed, stimulation may occur instead." (PMID 24315372, 2013). "An inappropriate increase in glucagon levels drives excess hepatic glucose output and contributes to hyperglycemia in type 2 diabetes." (PMID 24189067, 2013). "Clinically available GLP-1 receptor analogues, such as exenatide and liraglutide, are approved for treatment of type II diabetes since they reduce gastric emptying, glucagon secretion as well as enhance glucose-dependent insulin secretion." (PMID 24204788, 2013). "A significant and sustained increase in active GLP-1 with suppression of glucagon in response to vildagliptin has been reported in type 2 diabetes." (PMID 24188631, 2013). "Excessive secretion of glucagon, a functional insulin antagonist, significantly contributes to hyperglycemia in type 1 and type 2 diabetes." (PMID 23744070, 2013). "A similar pattern has also been observed in patients with type 1 and type 2 diabetes, and it was suggested that gastrointestinal factors contribute to the impaired glucagon response to OGTT." (PMID 23704713, 2013). "Analogues of this peptide recently emerged as novel pharmacotherapies for treatment of type II diabetes since they reduce gastric emptying, glucagon secretion as well as enhance glucose-dependent insulin secretion." (PMID 24204788, 2013). "Consistently, reduction in GCGR expression using ASOs significantly decreased blood glucose, circulating triglyceride, free fatty acids, and improved glucose tolerance by diminishing glucagon actions in type 2 diabetes prone db/db mice." (PMID 23316165, 2012).
type 2 diabetes (continued). "Evidence supporting this notion is consistent with clinical observations that α-cell insulin resistance exaggerates glucagon responses to stimuli in type 2 diabetic patients." (PMID 23316165, 2012). "Patients with type 2 diabetes exhibit multiple pathophysiological deficits, including declining ß-cell function and a failure to suppress postprandial glucagon secretion." (PMID 22564709, 2012). "The levels of MIF, insulin, ghrelin, leptin, glucagon, resistin and adipsin are similar in type 2 diabetes and CHD patients whereas IL-1α, IL-2R, IL-12, IL-18, HGF, and PAI-1 are higher in CHD patients than in type 2 diabetes patients (with p-value <0.01)." (PMID 22745767, 2012). "Preclinical studies demonstrated that chronic glucagon perfusion resulted in hyperglycemia, glomerular abnormalities, and impaired glucose tolerance, which are symptoms of early stage type 2 diabetes." (PMID 23316165, 2012). "Worsening hyperglycaemia in type 2 diabetes may result from a number of inter-related pathologies, including decline in beta-cell function, insulin resistance, increased hepatic glucose production associated with inappropriately high levels of glucagon and reduced GLP-1 production." (PMID 23061886, 2012). "Abnormal glucagon signaling contributes to hyperglycemia of type 2 diabetes; glucagon signaling is thus an obvious target for treating type 2 diabetes." (PMID 21853126, 2011). "This incretin hormone stimulates beta cell insulin secretion in a glucose-dependent manner, lowers glucagon, reduces appetite and reduces body weight, effects beneficial in type 2 diabetic patients." (PMID 19627582, 2009). "In the correlation between plasma glucagon levels and clinical factors, a positive correlation was seen with plasma glucose, serum osmolality and creatinine in both type 1 and type 2 diabetes patients in the DK/DKA group, a result reflecting hypovolemia and disease severity." (PMID 41292690, 2026). "Inhibit glucagon mediated cAMP formation and hyperglycemia in Type 2 diabetes." (PMID 41561889, 2026). "The parameters representing insulin resistance, glucagon secretion and suppression for an individual with normoglycaemia obtained from previously published work were evolved over a period of 20 years to the mean values observed in type 2 diabetes." (PMID 40924110, 2025). "Furthermore, some dedifferentiated β-cells co-express insulin and glucagon or glucagon alone both in rodents and in humans with type 2 diabetes, suggesting the transdifferentiation of β-cells into α-cells." (PMID 39860066, 2025). "Glucagon secretion is reported to be dysregulated in both type 1 and type 2 diabetes." (PMID 40354133, 2025). "PDAC-DM can resemble recent-onset type 2 diabetes early on, so dynamic testing may be required to uncover low β-cell output, higher insulin clearance, and inadequate postprandial glucagon suppression (α-cell dysregulation)." (PMID 41226286, 2025). "The approved GLP-1R agonists are peptide-based molecules that mimic the action of endogenous GLP-1, enhancing glucose-dependent insulin secretion, suppressing glucagon release, delaying gastric emptying, and thereby improving glycemic control in patients with type 2 diabetes." (PMID 41303737, 2025). "Tirzepatide enhances glucose-dependent insulin secretion, reduces glucagon levels, delays gastric emptying, and improves insulin sensitivity, making it a promising therapeutic option for managing both hyperglycemia and obesity in patients with type 2 diabetes." (PMID 40864047, 2025). "Previously, the coexpression of insulin and glucagon was observed only in a small proportion of islet cells in nondiabetic subjects, and some increase in the number of such cells was detected in persons with type 2 diabetes." (PMID 39860066, 2025).